WNT3A (Wnt family member 3A)
Diseases named in the same sentence as WNT3A in open-access papers (continued):
Sharing a sentence is not in itself a finding about the gene and the disease.
kidney cancer (1 paper, 2022). Primary or metastatic malignant neoplasm involving the kidney. "Kidney cancer (KC) and KT organoids ceased to proliferate and became extinct within 1–3 weeks without Wnt3A, whereas KCT and KCTS organoids stopped proliferating but survived and grew without exogenous Wnt3A after multiple passages." (PMID 35856555, 2022).
liver cirrhosis (1 paper, 2019). "However, no significantly difference (P>0.05) was found between Wnt3a and HCC patients' age, gender, tumor size, AFP level, liver cirrhosis, or gross classification." (PMID 31737122, 2019).
lung diseases (1 paper, 2024). "Wnt3a has been shown to stabilize Nrf2 in fibrotic lung diseases and alter antioxidant metabolism in hepatocytes." (PMID 38671839, 2024).
lymphoma (1 paper, 2016). A malignant (clonal) proliferation of B- lymphocytes or T- lymphocytes which involves the lymph nodes, bone marrow and/or extranodal sites. "The SP cells in lymphoma export Wnt3a via exosomes to neighboring cells, thus modulating population equilibrium." (PMID 26918831, 2016).
melasma (1 paper, 2022). "Some genes related to the Wnt/β-catenin pathway showed different behavior in fibroblasts from the skin with melasma, in relation to photoexposed adjacent skin; the DKK3 inhibitory factor was down-regulated, while WNT3A was overexpressed." (PMID 35840442, 2022).
myelomeningocele (1 paper, 2020). Myelomeningocele is the most severe form of spina bifida. "The carboxypeptidase E (CPE) gene on chromosome 4, which may affect binding of WNT3A to the target cell’s receptor, associated with myelomeningocele in the MA population." (PMID 32970752, 2020). "Therefore, the likely deleterious variants found in PORCN in our MA myelomeningocele population may prevent WNT3A from leaving the endoplasmic reticulum, ultimately downregulating all WNT signaling pathways in the target cell because less WNT3A would be secreted." (PMID 32970752, 2020).
osteomyelitis (1 paper, 2020). An acute or chronic inflammation of the bone and its structures due to infection with pyogenic bacteria. "In this study, we could demonstrate enhanced bone formation in defects caused by post-traumatic osteomyelitis after Wnt3a application." (PMID 32424558, 2020). "Our focus was to evaluate the regenerative capacity of Wnt3a-treated mice in a murine post-traumatic osteomyelitis model." (PMID 32424558, 2020). "The findings of this study could show the beneficial effects of Wnt3a application on bone regeneration after post-traumatic osteomyelitis." (PMID 32424558, 2020).
osteosclerosis (1 paper, 2021). Abnormally high bone density. "Osteocytes can secrete osteosclerosis, Wnt3a, and prostaglandins, regulate Wnt/β-catenin pathway, and affect the metabolism and functions of bones and muscles, respectively." (PMID 34163374, 2021).
Peri-Implantitis (1 paper, 2022). An inflammatory process with loss of supporting bone in the tissues surrounding functioning DENTAL IMPLANTS. "Instead of Wnt3A, Wnt5A expression was found to be upregulated in the gingival tissues with peri-implantitis." (PMID 35491409, 2022).
preeclampsia (1 paper, 2026). Preeclampsia is a hypertensive disorder of pregnancy that is characterized by new-onset hypertension with proteinuria presenting after 20 weeks of gestation, and depending on mild or severe forms may initially present with severe headache, visual disturbances, and hyperreflexia. "TGIF1 and its targets, including ADAM12, WNT3A, and ZNF831, are associated with preeclampsia and pregnancy loss." (PMID 42103736, 2026).
pulmonary emphysema (1 paper, 2018). A subcategory of chronic obstructive pulmonary disease (COPD). "In conclusion, Nrf2 mediates the protective effects of both Wnt3a/β‐catenin and AMPK on lung inflammatory responses during the development of COPD/emphysema." (PMID 29659176, 2018). "We hypothesize that Wnt3a/β‐catenin and AMPK co‐regulate Nrf2, thereby modulating lung inflammatory and injurious responses during the development of COPD/emphysema." (PMID 29659176, 2018).
pulmonary hypertensive (1 paper, 2011). "Expression of Wnt ligands (Wnt1, Wnt3a, and Wnt5a) and Wnt signaling upstream regulator genes (Frizzled1 and 2 receptors and sFRP-1) and intracellular effectors (Axin1 and GSK3β) were investigated in pulmonary hypertensive rat lungs, 3 and 5 weeks after MCT injury." (PMID 21533110, 2011).
rectal adenocarcinoma (1 paper, 2019). "TIPE2 overexpression increased apoptosis through down‐regulating the expression levels of Wnt3a, phospho (p)‐β‐Catenin, and p‐glycogen synthase kinase‐3β in rectal adenocarcinoma cells, however, TIPE2 knockdown exhibited reverse trends." (PMID 30637920, 2019).
renal carcinoma (1 paper, 2016). A carcinoma arising from the epithelium of the renal parenchyma or the renal pelvis. "Moreover, down-regulation of SOSTDC1 was observed in renal cancer, and SOSTDC1 could suppress the proliferation of renal cancer cells via regulating BMP and Wnt3a signaling." (PMID 27087917, 2016).
retinal degeneration (1 paper, 2018). Degeneration of the retina. "Further, previous studies have shown that activation of Wnt/β-catenin signalling via intravitreal injection with recombinant Wnt3A induced RGC survival in a mouse model of axon crush injury and preservation of photoreceptors in a mouse model of inherited retinal degeneration." (PMID 30019207, 2018).
scoliosis (1 paper, 2024). A congenital or acquired spinal deformity characterized by lateral curvature of the spine. "A kinky tail phenotype has been observed for several genes associated with scoliosis, including Wnt3a,48Axin1,49,50Sox9,51 and Pax1." (PMID 38461417, 2024).
Shock (1 paper, 2015). The state in which profound and widespread reduction of effective tissue perfusion leads first to reversible, and then if prolonged, to irreversible cellular injury. "We found the lung from rats with endotoxic shock exhibited significant decreases in the levels of Wnt3a, Fzd1, Dsh1, phosphorylated GSK-3β at Ser9, total β-catenin, and nuclear β-catenin when compared with the Control group." (PMID 26218875, 2015).
silicosis (1 paper, 2020). Silicosis is a respiratory disease caused by breathing in (inhaling) silica dust. "Moreover, the increased abundances of Wnt3a, NOX4, α-SMA, and vimentin were further corroborated to be predominantly expressed in the silicosis nodules of silica-challenged lungs as determined by the immunofluorescent staining (IF) assay." (PMID 33376577, 2020).
Stillbirth (1 paper, 2007). Death of the fetus in utero after at least 22 weeks of gestation. "Although our pilot study included 5 stillbirth samples and no mutations in WNT3A were detected, a larger cohort of stillbirth samples with vertebral malformations would be needed to determine whether mutations in WNT3A are prevalent among stillbirths with congenital vertebral malformations." (PMID 17888180, 2007).
Urethral stricture (1 paper, 2023). Narrowing of the urethra associated with inflammation or scar tissue. "We observed an overexpression of the Wnt proteins Wnt3a, β-catenin and also a significantly decreased expression of the the endogenous inhibitor DKK1 in human urethra tissues derived from patients with urethral stricture." (PMID 37859694, 2023).
Zinc deficiency (1 paper, 2025). A deficiency of the essential metal Zinc; an essential cofactor for many enzymes. "Our results indicate that zinc deficiency reduces specific markers of podocytes (podocalyxin, WT1, and nephrin) and activates the Wnt3a/β-catenin pathway, a key pathway in podocyte injury." (PMID 39028478, 2025).
tumor (181 papers, 2008 to 2026). "The elevated expression of Wnt3a in HCC has been linked to poor tumor differentiation, liver cirrhosis, hepatitis B virus (HBV) infection, advanced TNM stage, and reduced OS." (PMID 40943055, 2025). "Previous studies have shown that Wnt/β-catenin signaling promoters such as Wnt1, Wnt2 and Wnt3a are associated with tumor proliferation and angiogenesis in NSCLC." (PMID 34465343, 2021). "The cluster of miR-15a/miR16-1 was reported to target Bcl-2, CCND1 (encoding cyclin D1) and WNT3A, leading to tumor cell growth arrest and apoptosis." (PMID 27151407, 2016). "Wnt3a expression is associated with the expression of MMP-9 in primary tumor tissue adjacent mesenchymal tissue, and at the metastatic site." (PMID 24564183, 2014). "Notably, this tissue-specific conditional silencing of CD44v6 resulted in long lasting effects on self-renewal and tumor growth associated with a positive feedback loop linking WNT3A signaling and alternative-splicing of CD44." (PMID 35982950, 2022). "Moreover, a cluster of biomarkers induced by Wnt3a in HepaRG cells reflecting progenitor cells with mesenchymal commitment was associated with high Edmondson-Steiner's score in HCCs, indicating poor tumor differentiation." (PMID 27191501, 2016). "Aberrant hyperactivation of WNT3a has been shown to be closely associated with tumor progression and clinical grade in various cancer types, however its mechanism of action varies significantly depending upon tumor type." (PMID 27391060, 2016). "In addition, ectopic expression of E-cadherin in HM20 cells (102 cells) significantly inhibited Wnt3a-elicited tumor initiation, whereas ectopic expression of endocytosis-deficient E-cadherin diminished effects against Wnt3a-elicited subcutaneous tumor growth." (PMID 26075748, 2015). "Wnt3a and Wnt7a are likewise upregulated in metastatic breast cancer cell lines in association with poor prognosis and inhibition of Wnt/β-catenin signaling via Wnt1 knockdown could efficiently suppress cell proliferation and tumor growth." (PMID 33585487, 2021). "This study aimed to evaluate the expression of Wnt/β-catenin pathway components and tumor-associated markers-including COX-2, Ki-67, tryptase, CD1a, and WNT3A-across different histopathological subtypes of BCC." (PMID 42194765, 2026). "In vivo, CAFs promoted CRPC tumor growth and significantly increased the expression of Wnt3a, β-catenin, TCF4, LEF1, SDF-1, and CXCR4, along with an elevated p-GSK-3β/GSK-3β ratio." (PMID 40735647, 2025). "In the isogenic-paired cell lines, SM08502 effectively inhibited tumor cell viability at nanomolar ranges in the sensitive, resistant, and WNT3A-overexpressing cell lines." (PMID 41340358, 2025). "TOP2A interacts with Wnt3a to activate the Wnt signaling pathway, promoting tumor formation, progression, and metastasis." (PMID 40777026, 2025). "As with most tumor organoids, the addition of common growth factors such as wnt-3a, noggin, R-spondin-1 to MPMO culture is beneficial to its development." (PMID 38200517, 2024). "MiR-15a-5p, as a suppressor of tumour formation, promotes apoptosis and inhibits tumour growth by targeting specific oncogenes, such as Bcl-2, CcnD1, Mcl1, and Wnt3A." (PMID 38698968, 2024). "Other studies have found that Wnt3a not only promotes tumor metastasis through the Wnt/β-catenin signal but also induces Rho kinase and PLC-dependent cell migration by activating PLC 52,55." (PMID 38706907, 2024). "Significantly upregulated mRNA and protein expression of SALL4, Wnt3a and β-catenin in HCC tissues is associated with tumor differentiation, the TNM stage, tumor size, vascular invasion and liver cirrhosis in HCC patients." (PMID 38584262, 2024). "A similar observation was made in HCC and CRC mouse models, where addition of recombinant WNT3A to tumor-derived T cells increased expression of β-Catenin and decreased expression of the CTL differentiation marker T-bet." (PMID 36982422, 2023).
tumor (continued). "Immunohistochemical analysis of 38 iCCA cases detected Wnt3a protein in the cytoplasm of tumor cells in 92.1% of cases, Wnt5a in 76.3% of cases, and Wnt7b in all tumors." (PMID 37190050, 2023). "In this study, higher WNT3A was detected in HOXB3 + tumors and was associated with higher tumor grade and stage." (PMID 36973255, 2023). "It has been shown that TOP2A and Wnt3a play an essential role in the development of NSCLC and tumor metastasis, and the expression of TOP2A and Wnt3a is closely related to tumor differentiation, TNM stage and the occurrence of lymph node (LN) metastasis." (PMID 37407689, 2023). "MM cells secrete inhibitors of the WNT3A canonical signal transduction pathway, and an increase in WNT3A in MM cells inhibits bone disease and tumor growth in SCID-nu mice." (PMID 37239457, 2023). "In this CRC mouse model, intratumoral administration of a WNT3A targeting antibody (aWNT3A) decreased tumor volume and an increased the proportion of tumor antigen-specific CTLs in the TME, which exhibited a higher expression of T-bet and IFN-γ." (PMID 36982422, 2023). "A large number of clinical and basic experiments have shown that the members of Wnt family, including WNT1, WNT2, WNT3A etc., are highly expressed in malignant tumour tissues, which can enhance tumour occurrence, growth and metastasis." (PMID 36646807, 2023). "Cells expressing EYA4 S37E had intact nuclear accumulation of β-catenin and Id2 transcription upon Wnt-3a stimuli, suggesting that Ser37 autophosphorylation restrains the tumor-suppressive phenotypes of EYA4." (PMID 36741265, 2023). "In turn, these stromal cells secrete Wnt ligands like Wnt3a, Wnt5a, and Wnt7b, and other factors that further activate Wnt signaling in tumor cells, creating a positive feedback loop that promotes tumor growth and progression." (PMID 37760801, 2023). "In order to further prove that NE can regulate the expression level of WNT7A, we detected the expression levels of Wnt1, Wnt2, Wnt3a, Wnt4, Wnt5a, Wnt6, Wnt7a and Wnt10a in tumour tissues of anti-PD-1 mAb + Vehicle and NE + anti-PD-1 mAb + Vehicle groups." (PMID 36646807, 2023). "The analysis of 48 cases of liver fluke-derived iCCA showed that mRNA levels of Wnt3a, Wnt5a, and Wnt7b were higher in the tumor tissue than in the surrounding liver tissue." (PMID 37190050, 2023). "We also observed a significant influence for better OS by higher SPARC and WNT3A expression in tumor stroma." (PMID 36452484, 2022). "Increasing evidence suggests that Wnt3A, depending on the cancer type, either stimulates or inhibits tumor growth via the canonical Wnt signaling pathway." (PMID 35865469, 2022). "We also observed that high SPARC and WNT3A expressions in the tumor stroma had a significant influence on OS (HR 0.55 for higher versus low expression, CI 0.30-1.00, P=0.050; HR 0.54 for higher versus lower expression, CI 0.30–0.99, P=0.046; respectively)." (PMID 36452484, 2022). "Since Wnt3a is an abundant growth factor in the CRC tumor microenvironment that is conducive to metastasis, this finding provides a rationale for why DKK4 is upregulated in tumors but plays a suppressive role." (PMID 36181792, 2022). "In vivo experiments showed that GLA inhibited EOC tumor growth, meanwhile, upregulated the miR-374b-5p level and downregulated the expression of HMGB3, Wnt3a, and β-catenin in tumor tissues." (PMID 35912216, 2022). "In summary, we found that miRNA-503 acts as a tumor suppressor in HNC by inhibiting cell invasion through the suppression of WNT3A." (PMID 36555553, 2022). "Wnt1 and Wnt3A have also been shown to have regulatory effects on immunity in different tumor microenvironments." (PMID 36091060, 2022). "WNT3A shRNA alone inhibited tumor cell proliferation to nearly the same extent as v6 shRNA at the highest concentration of FOLFOX treatment." (PMID 36330477, 2022).
tumor (continued). "PSPC1 also facilitates the cytoplasmic translocation of protein tyrosine kinase 6 (PTK6) to become an oncogene, and β-catenin nuclear translocation to interact with PSPC1 for augmenting Wnt3a autocrine signaling and tumor progression." (PMID 34359789, 2021). "A recombinant soluble peptide fragment (rhFzd7) has been shown to antagonize Fzd7 by competitively binding with Wnt3a and exhibit anti-tumor and anti-angiogenesis activities in TNBC." (PMID 33585487, 2021). "For example, Wnt signalling is known to contribute to tumour progression;36 however, Wnt3A from CAFs both promotes and inhibits development of patient-derived breast xenograft tumours." (PMID 33637678, 2021). "MIA PaCa-2 tumor-derived 3D cultured in the presence of Wnt3A showed a strong signal of active β-catenin concomitant to an increase of nuclear Cyclin D1 localization and accumulation." (PMID 34203710, 2021). "Screening for Wnt ligand expression by qPCR revealed that Wnt7b, Wnt9a and to a lesser extent Wnt3a, were significantly elevated in H2-c-fosLTR tumor-bearing bones and tumors." (PMID 32686768, 2020). "The interrelationship between GSK-3β/β-catenin has been described in the development of multidrug resistance in CCA and it is shown that Wnt3a activates GSK-3β/β-catenin signaling to up-regulate the expression of P-glycoprotein efflux pump on the tumor cells." (PMID 32140709, 2020). "WNT3A derived from GBM induces upregulation of stress-inducible protein 1 (STI1/HOP), interleukin 10 (IL-10), and arginase-1 (ARG-1) in tumor-associated microglia." (PMID 33312955, 2020). "Except to the activation of Wnt/β‐catenin signaling in tumor cells, WNT3A has also been reported to activate Wnt/β‐catenin signaling in macrophages and induce M2 macrophages polarization." (PMID 31785055, 2020). "In this context, a previous study using a murine model of prostate cancer has shown that administration of Wnt3a-neutralizing antibodies restrained tumor growth." (PMID 32132993, 2020). "Wnt3A-mediated pathway activation also reduced secondary tumor sphere size, frequency, and cell proliferation in non-Wnt MBs." (PMID 32859895, 2020). "Tumor-infiltrating T cells express markedly higher levels of Wnt3a and β-catenin, and display dysfunctional and exhausted effector memory phenotype." (PMID 32132993, 2020). "For example, tumor organoids derived from CRC can be selectively upon withdrawal of Wnt3a and R-Spondin1." (PMID 33135109, 2020). "For example, tumor organoids from colorectal cancer (CRC) can be selectively expanded upon withdrawal of Wnt3a and R-Spondin1." (PMID 33135109, 2020). "In another critical study, it was shown that administration of Wnt3a-neutralizing antibodies in tumor bearing mice restrains tumor growth by potently activating DCs and boosting the expansion of tumor-specific CD8+ T cells with improved effector activities." (PMID 32132993, 2020). "AKT/mTOR and Wnt3a/β-catenin, key pathways in regulating tumor proliferation and metastasis, were found to be inactivated by the down-regulation of PBF in ESCA cells." (PMID 31637306, 2019). "Among these tumor samples, 52 (23.4%) patients displayed high Wnt3a expression, 95 (42.8%) patients with middle Wnt3a expression and 75 (33.8%) patients with low Wnt3a expression." (PMID 31528227, 2019). "The aberrant increase in Wnt3a expression level has been previously reported in several human malignancies and has been correlated with tumor progression, recurrence, and metastasis, predicting worse clinical outcomes." (PMID 31528227, 2019). "Evidence for CRISPR/Cas Wnt7b gene inactivation is shown by the significantly reduced transcription of the canonical WNT signalling target Axin2 in edited tumour cells which can be rescued by WNT3a supplementation." (PMID 30926782, 2019). "Wnt3a enhanced the tumor-initiating capacity of Caco-2/E12 and Caco-2/E47 cells to the levels of Caco-2 cells." (PMID 31234887, 2019).